RPL32P3 (ribosomal protein L32 pseudogene 3)
Gene: Transcribed unprocessed pseudogene on chromosome 3 (129,396,218 to 129,397,109, reverse strand). Ensembl gene ENSG00000251474.
Diseases named in the same sentence as RPL32P3 in open-access papers:
RPL32P3 is named in the same sentence as 4 diseases in open-access papers, as found by Europe PMC text mining. Sharing a sentence is not in itself a finding about the gene and the disease. The quoted sentences say what the papers report.
glioma (1 paper, 2021). A benign or malignant brain and spinal cord tumor that arises from glial cells (astrocytes, oligodendrocytes, ependymal cells). "In this study, we identified that ribosomal protein L32 pseudogene 3 (RPL32P3) was highly expressed in glioma-exposed endothelial cells (GECs)." (PMID 34819492, 2021). "The combination of simultaneous knockdown of RPL32P3, YBX2, and HNF4G with DOX significantly induced U251 glioma cells apoptosis and produced the strongest effects." (PMID 34819492, 2021). "The simultaneous knockdown of RPL32P3, YBX2, and HNF4G combined with doxorubicin (DOX) increased the apoptosis of glioma cells." (PMID 34819492, 2021). "The results suggested that the combined application of knockdown of RPL32P3, YBX2, and HNF4G could promote the passage of DOX through BTB and enhance the inhibitory effect of DOX on glioma cells." (PMID 34819492, 2021). "In this study, by establishing the BTB model in vitro, we found that the simultaneous knockdown of RPL32P3, YBX2, and HNF4G combined with DOX could significantly increase the apoptosis rate of glioma cells." (PMID 34819492, 2021).
metastatic prostate carcinoma (1 paper, 2023). A carcinoma that arises from the prostate gland and has spread to other anatomic sites. "A total of 163 transcripts comprising 161 genes, a pseudogene (RPL32P3), and an oncogenic lncRNA (MALAT1) were found to be significantly elevated in patients with metastatic prostate cancer compared with localized cases." (PMID 37812088, 2023).
cancer (2 papers, 2019 to 2021). A tumor composed of atypical neoplastic, often pleomorphic cells that invade other tissues. "The results demonstrated that SNORA7B was up-regulated in all BC cell lines compared with its expression in normal breast cell line MCF10A, while RPL32P3 was overexpressed in only two cancer cell lines compared to MCF10A." (PMID 31168298, 2019).
RPL32P3 also shares sentences with these, for which no sentence is quoted: tumor (1 paper).